EGFR (epidermal growth factor receptor)
Diseases named in the same sentence as EGFR in open-access papers (continued):
Sharing a sentence is not in itself a finding about the gene and the disease.
tumor (continued). "Up to 19% of HNSCC also overexpress the human epidermal growth factor receptor 2 (HER2) gene, thereby revealing an interesting opportunity to examine anti-EGFR and anti-HER2 dual treatment synergy to reduce HNSCC tumor burden." (PMID 38355949, 2024). "MYO10 is overexpressed in EGFR-overexpressing GBMs52, and GBM mouse models indicate that MYO10 supports malignancy because knockout of MYO10 impairs GBM invasion, slows tumor proliferation, reduces integrin-related signaling and prolongs survival." (PMID 38773237, 2024). "Overall, it is a well‐planned and refined study that comprehensively demonstrated TMEM25 as a tumor suppressor protein that prevents the interaction of monomeric EGFR with STAT3 and thereby suppresses STAT3 phosphorylation and tumor progression." (PMID 38532948, 2024). "In one study of 119 surgical tumor specimens, 14% of tumors that were classified as HER2-positive were EGFR-positive." (PMID 38711454, 2024). "Axl and EGFR are co-expressed in NPC tissues and play key roles in tumor proliferation, migration, and invasion, which are often correlated with poor prognosis and therapy resistance." (PMID 39594573, 2024). "CSF: cerebrospinal fluid; LC: leptomeningeal carcinomatosis; cfDNA: cell-free DNA; EGFR: epidermal growth factor receptor; CTC: circulating tumor cells." (PMID 38558729, 2024). "We further observed a significantly higher MDA level in EGFR or ErbB2 overexpressed tumor tissues than vector control tumor tissue upon IKE treatment, suggesting more ferroptosis is induced by IKE treatment in EGFR or ErbB2 overexpressed tumor tissues." (PMID 39604370, 2024). "The tumor biopsies of PDX-P3 indicated a highly elevated Myc and EZH2 gene expression and 4-fold EGFR gene amplification." (PMID 38553638, 2024). "Delivery of the anti-epidermal growth factor receptor (EGFR) targeted carboxymethyl chitosan nanoparticles, directly labeled with Na131I (ICED-N), achieved deep tumor penetration in a three-dimensional model." (PMID 38338373, 2024). "Targeted NGS with plasma circulating tumor DNA (ctDNA) detected PIK3CA M1004I and the EGFR 19 deletion." (PMID 38398169, 2024). "The findings revealed that treatment with hemagglutinine resulted in downregulation of CD34, Ki67, EGFR, Bcl-2, and VEGF expressions in tumor tissues while up-regulating the pro-apoptotic protein Bax expression." (PMID 38751791, 2024). "Erlotinib is a targeted therapy drug, which belongs to the epidermal growth factor receptor (EGFR) tyrosine kinase inhibitor (TKI) class, by inhibiting the activity of EGFR, thereby preventing the growth and spread of tumor cells." (PMID 38974045, 2024). "She received erlotinib treatment after the detection of coexistent EGFR L858R/G719S and BRAF V600E via next-generation sequencing of resected tumor tissue." (PMID 39135785, 2024). "When loaded with EGFR-siRNA, LPX + UTMC suppressed EGFR expression and inhibited tumor growth in vivo, suggesting that this platform holds promise for non-invasive, image-guided targeted delivery of therapeutic siRNA for cancer treatment." (PMID 38577322, 2024). "Based on our data, CD8 Tex cells in LN-out upregulate of TGF-β1, IFN-γ, and ITG-β1, which subsequently target FN1, EGFR, CTNNB1, and COL1A1 in tumor cells, activating the ERK1 and ERK2 cascade pathways and facilitating tumor progression." (PMID 38519500, 2024). "C1Qhigh TAMs interact principally with aDTCs via the epiregulin-epidermal growth factor receptor (EGFR) and CD226-NECTIN2 receptor–ligand pairs, which are involved in tumor-cell survival and proliferation." (PMID 38460015, 2024). "Curcumin also reduces the activation of the epidermal growth factor receptor (EGFR) signaling pathway, which is responsible for cell proliferation and tumor growth." (PMID 39519045, 2024). "This, in turn, allows miR-133a to suppress the PAM signaling pathway in tumor cells by reducing the expression of EGFR and PIK3C2A targets, ultimately resulting in decreased growth and development of tumor cells." (PMID 38504785, 2024).
tumor (continued). "The overexpression of EGFR, MPS-1, Aurora-B, and KSP in OSCC underscores their critical roles in tumor progression." (PMID 39594688, 2024). "By activating EGFR signaling, but also by shedding RTKs on the cell surface, ADAM17 plays a crucial role in mediating intracellular signal transduction and promotes tumor proliferation, migration and metastasis." (PMID 39506058, 2024). "By inhibiting EGFR, it is possible not only to reduce VEGF expression but also to disrupt the growth and survival mechanisms of tumor cells, which contributes to decreasing angiogenesis." (PMID 39598438, 2024). "Distinct cell clusters of EGFR-high and CCNE1-high cells were found predominantly in the EpCAM+ clusters in TNBC, where EGFR was expressed in 23.1% ± 1.6% of EpCAM+ cells, compared with 4.4% ± 0.7% in HER2+ and 3.5% ± 0.5% in ER+ tumor cells." (PMID 38772416, 2024). "Simultaneous targeting of PD-L1 and EGFR by bispecific antibodies promotes PD-L1 blockade selectively in the TME due to EGFR overexpression in malignant cells, while reducing potential off-tumor binding to normal PD-L1-expressing cells." (PMID 38804302, 2024). "Therefore, METTL1 may act as a target to enhance the anti‐tumor activity of EGFR‐TKIs." (PMID 38967523, 2024). "The findings above indicate that EGFR, GP73, and PD-L1 synergistically promote cancer, promising that combining EGFR inhibitors with PD-L1 antibodies can reverse GP73-mediated effects, enhancing CD8+ T cell infiltration and inhibiting tumor growth." (PMID 39845976, 2024). "We demonstrated that EGFR and MUC1 were co-expressed on tumor cells in the majority of LUAD and CRC clinical samples." (PMID 39664199, 2024). "An experimental study was conducted before and after injection of anti-EGFR -MPB using 2 filter modes to image blood vessels (532 to 1,000 nm) and the nanocomposite to evaluate the impacts of anti-EGFR-MPB (625 to 1,000 nm) on tumor-specific binding affinity." (PMID 39525484, 2024). "Maraver’s lab recapitulated this acquired molecular resistance mechanism by generating an EGFR/MET transgenic mouse model and showed the addition of MET inhibitors to osimertinib-induced tumor regression." (PMID 39796653, 2024). "Given the dominant role of CD8+ T cells in anti-tumor activity, we compared CD8+ T cells infiltration between EGFR mutant and wild-type tumors." (PMID 39004699, 2024). "In line with previous studies, co-expression of EGFR and MUC1 in the same tumor cells was found in most cases, including 63 (98.4%) LUAD and 76 (91.6%) CRC samples." (PMID 39664199, 2024). "In turn, CD8 Tex cells in the LN-out highly expressed TGF-β1, IFN-γ, and ITGB1, which target FN1, EGFR, CTNNB1, COL1A1, and CFLAR in tumor cells, activating downstream pathways including ERK1 and ERK2 cascade." (PMID 38519500, 2024). "These DRT radiation nanomedicines were intended to overcome receptor heterogeneity in BC tumours and exploit the co-expression of HER2 and EGFR by some trastuzumab-resistant BC cells." (PMID 38703297, 2024). "Another study has shown that atorvastatin exhibits anti-tumor properties in NSCLC and can overcome resistance to EGFR-TKIs." (PMID 39308527, 2024). "The EGFR and PD-L1 gene expression profiles across all HNSCC tumor samples (n = 519) and paired normal tissues (n = 44) were expressed as log2[transcripts per million (TPM) + 1]]." (PMID 39183296, 2024). "In a study on EGFR-specific CAR-T cells for the treatment of NSCLC, researchers constructed EGFR-CAR-T cells using genetic engineering and established a subcutaneous tumor model of NSCLC in NSG mice." (PMID 38919533, 2024). "ACEA inhibits epidermal growth factor receptor signaling and altered tumor microenvironment (TME) by activating CB1 to induce tumor cell death." (PMID 38350727, 2024). "Combination treatment using anti-CD3 and anti-HER2 bispecific antibody together with EGFR inhibitor reduced MDSC Arg1 expression, leading to increased levels of Th1 cytokine-mediated anti-tumour immunity." (PMID 38464388, 2024).
tumor (continued). "Many other oncogenes, including BCL-2, SOX-2, HBXIP, EGFR, BRD4, LGR5, c-MYC, and MYB are upregulated in an m6A dependent manner leading to tumor progression in multiple cancers." (PMID 39087001, 2024). "Finally, we have assessed whether afatinib, a second generation TKI could be used to treat tumor relapse since adding afatinib to osimertinib could help overcome EGFR-dependent osimertinib resistance, such as secondary C797S mutation or other co-existing EGFR mutations." (PMID 38935790, 2024). "Autosecretory TGF‐α stimulation does lead to increased tumor growth in vivo, regulated through the TGF‐α/EGFR autocrine circuit, which can be accessed." (PMID 39346787, 2024). "There are 42 intersecting targets of cancer/tumor with PKVG phenolic acid-based active ingredients, and the top four DC were MAPK1, EGFR, MAPK10, and PRKCA by network analysis." (PMID 39689118, 2024). "Cas13-based SHERLOCK can detect cell-free tumor DNAs including BRAF V600E and epidermal growth factor receptor (EGFR) L858R." (PMID 39189452, 2024). "ADAMTS1 acts as a tumor metastasis promoter in OSCC, and L1CAM and EGFR are critical determinants regulated by ADAMTS1 when executing its prometastatic effect via EMT induction." (PMID 38263290, 2024). "The EGFRxHER2 T-BsAb mediated cytotoxicity against EGFR-KO and HER2-KO lines with sensitivities comparable to the ‘tumor monovalent’ T-BsAbs HER2xCD33 and EGFRxCD33 respectively." (PMID 38650005, 2024). "It is feasible that upregulation of EGFR and MET in tumor cells contributed to resistance to pembrolizumab monotherapy." (PMID 38916448, 2024). "We found that CHST2 and the well-known target genes of the proposed drugs, HRH1, and EGFR/ERBB2, were co-expressed in the GBM tumours as shown in iNetModels." (PMID 39063109, 2024). "Although EGFR TKIs have revolutionized the field of EGFR-mutant NSCLC therapy, acquired resistance inevitably occurs due to tumor heterogeneity and adaptability." (PMID 39143065, 2024). "The activity of SRPK1 is closely related to the expression and function of various tumor-related genes, including EGFR (epidermal growth factor receptor), VEGF (vascular endothelial growth factor), and others." (PMID 38397980, 2024). "The upregulation of these molecules facilitates the recruitment of anti-tumor T-cells and triggers an immune response accompanied by the release of pro-inflammatory molecules like IL-1, IL-2, IL-6, IL-8, IL-12, VEGF, EGFR, IFN-α, IFN-ß and TNF-α." (PMID 39518094, 2024). "CMTM3 can promote the degradation of EGFR to reduce its expression, activate caspase-3 to induce cell apoptosis, and partially inhibit the JAK2/STAT3 signaling pathway to suppress tumor cell proliferation." (PMID 38223763, 2024). "Clinical trials are currently investigating combinations of EGFR inhibitors with PD-1/PD-L1 blockade therapies and EGF tumor vaccines." (PMID 38654302, 2024). "The immunogenicity of MET-amplified EGFR-TKI-resistant cells is enhanced, and STING induction and T-cell reactivity in tumor cells are promoted by inhibiting CD73." (PMID 38566036, 2024). "On the other hand, overexpression of METTL14 in cells can inhibit the EGFR/PI3K/AKT signaling pathway in an m6A methylation-dependent manner, thereby suppressing tumor metastasis." (PMID 38965238, 2024). "For example, GE11 peptide-modified EVs deliver let-7a miRNA to EGFR-expressing xenograft breast tumors, inhibiting the expression of HMGA2 mRNA and thus the tumor development in vivo." (PMID 38796692, 2024). "Our results indicated that both EGFR and MPS-1 mRNA levels were significantly overexpressed in the SCC-25 cell line compared to the non-tumor cell line HOK (25-fold increase and 1.5-fold increase for EGFR and MPS-1, respectively)." (PMID 39594688, 2024). "Then, we assessed the significance of EP300 for the prognosis of LUAD by conducting Cox regression analysis of covariates, including gender, age, tumor size, tumor grade, T and N staging, and expression of PDL1, ALK, EGFR, and EP300." (PMID 38256128, 2024).
tumor (continued). "There are several bs-Abs that have the ability to alter various aspects of cancer TME, including tumor proliferation, angiogenesis, metastasis, and immunosuppression by targeting signaling pathways such as HER1, HER2, HER3, EGFR, TGF-β and VEGF." (PMID 39609700, 2024). "CD19, epidermal growth factor receptor (EGFR) and B cell maturation antigen (BCMA) are effective anti-tumor targets in clinical practice." (PMID 38933272, 2024). "Members of the ErbB tyrosine kinase family such as EGFR and HER2 are frequently altered in cancer, driving tumor growth and progression through aberrant signaling pathways." (PMID 39464883, 2024). "For example, epidermal growth factor receptor (EGFR) inhibitors, such as cetuximab, inhibit tumor cell growth and division by interfering with the EGFR signaling pathway." (PMID 38645557, 2024). "significantly downregulated the protein and mRNA levels of Epidermal Growth Factor Receptor (EGFR), VEGF and the Cluster of Differentiation 34 (CD34) transmembrane cell-cell adhesion factor in tumour-bearing BALB/c mice, thereby inhibiting tumour growth." (PMID 39683144, 2024). "In particular, exosomes contain a variety of tumor‐related protein markers, such as human epidermal growth factor receptor 2(HER2), EGFR, glypicans, integrin, and programmed death ligand 1 (PD‐L1)." (PMID 39247621, 2024). "The strongest downregulation with PDD feeding was observed for stet (EGFR pathway), AKAP200 (Notch), and cycE (JAK/STAT), whereas the strongest upregulation in tumor development was observed for upd1 (JAK/STAT pathway)." (PMID 37962464, 2024). "Epidermal growth factor receptor (EGFR) inhibitors and immune checkpoint inhibitors have emerged as novel and potent anti-tumor therapies in recent years." (PMID 38237211, 2024). "EGFR and HER2 T-BsAbs were also heterodimerized with a CD33 control T-BsAb to generate ‘tumor-monovalent’ EGFRxCD33 and HER2xCD33 T-BsAbs." (PMID 38650005, 2024). "We further validated the expression of EGFR by IF staining, showing EGFR staining primarily in HNF4A+ regions, underscoring the critical role of EGF signaling in fetal tumor cells." (PMID 39567475, 2024). "Pin‐point targeting of the key modulator in LC like epidermal growth factor receptor (EGFR), anaplastic lymphoma kinase, or ROS proto‐oncogene‐1 (ROS1) are promising features of some tumor‐specific therapeutic agents." (PMID 39584048, 2024). "Although our preclinical studies showed that EGFR BATs maintain their cytotoxicity after radiation and TMZ, it is possible that TMZ blunted the anti-tumor effect of immunotherapy." (PMID 38263486, 2024). "For example, targeting HIF1A along with EGFR or VEGF inhibitors can disrupt both hypoxia adaptation and angiogenesis, which is crucial for tumor growth and metastasis." (PMID 39458948, 2024). "Co-inhibition of EGFR and TEAD by osimertinib and VT104, respectively, has previously been shown to enhance osimertinib tumor response in NSCLC models." (PMID 38565920, 2024). "miR-126 reconstitution partially restored the protease balance in CRC and CAC tumor and myeloid cells that control the expression status of HB-EGF and EGFR." (PMID 39419989, 2024). "The anti-CD3 domain is selected for the variable domains on the unmodified side and the anti-tumor target domain (anti-CD19, anti-EGFR, anti-BCMA) is assembled in the variable domains on the modified (PHE1) side." (PMID 38933272, 2024). "Decorin can target multiple tyrosine kinase receptors, such as c-met, EGFR, and IGFR, which play important roles to support tumor growth and promoting tumor metastasis." (PMID 39306655, 2024). "Individuals with tumor driver genes have been gradually revealed in NSCLC patients, with notable examples such as the epidermal growth factor receptor (EGFR) and the anaplastic lymphoma kinase (ALK)." (PMID 38238722, 2024).
tumor (continued). "This evidence is in line with our findings, as we observed that the EGFR-mutant NSCLC cell line H1975 accumulated in G2–M, slowed down its in culture proliferation ability, and showed tumor growth inhibition in xenograft models, upon treatment with Unesbulin." (PMID 38546390, 2024). "MYC, EGFR and KIT are among such genes with late gains in both OS and BRCA, emphasizing their ability in stimulating cell multiplication in multiple tumor types." (PMID 38448455, 2024). "We analyzed the differential expression levels of EGFR and USP21 in CRC tumor tissues compared to matched normal tissues from these patients." (PMID 39695128, 2024). "Our study shows that EGFR BATs were produced from PBMC of patients with AG4 before receiving concomitant RT/TMZ, but that in some instances, T cell expansion was limited by tumor-induced immunosuppression or other inherent T cell dysfunction." (PMID 38263486, 2024). "The ability of HPV8 E6 to transform keratinocytes has been studied for other binding partners affecting tumor suppressor and oncogenic pathways: Notch, TGF-β, Hippo, EGFR, and Wnt." (PMID 38916963, 2024). "According to the GEPIA dataset, the expression levels of EGFR and PD-L1 were significantly higher in HNSCC tumors than para tumor tissues." (PMID 39183296, 2024). "When combined with EGFR-CAR-NK cells, this increased persistence of CAR-NK cell activity synergistically suppressed tumor growth and significantly improved survival rates." (PMID 39055561, 2024). "In the present study we aimed to identify tumor markers specific for ALK‐positive NSCLC by comparing tumor marker levels between patients with ALK‐positive and EGFR‐positive NSCLC." (PMID 38400801, 2024). "Additinally, the knockdown of KLF4 in the SW480 CRC cell line induced the YAP pathway and its downstream genes, including EGFR, MYC, BIRC5, and CTGF, leading to tumor proliferation." (PMID 38167453, 2024). "When combined with gefitinib, a small-molecule EGFR inhibitor, TAK-701 effectively suppresses the phosphorylation of both c-MET and EGFR, along with their downstream signaling pathways, in HCC827-HGF tumor cells." (PMID 39664377, 2024). "A key aim of this trial was to explore the immunomodulatory effects of combination EGFR TKI and PD-1 therapy on both circulating immune cells and the tumor immune microenvironment." (PMID 39318388, 2024). "By binding directly to EGFR, it activates the EGFR/ERK1/2/c-Jun signalling pathway, promoting tumour cell proliferation and migration while also upregulating PD-L1 expression, which aids in immune evasion." (PMID 39063109, 2024). "EGFR and PD-L1 double IF staining also confirmed their high expression in the CAL27-Fluc mouse tumor xenografts." (PMID 39183296, 2024). "For instance, exosomes appear to promote tumor growth and metastasis by delivering molecules, such as TGF-β, EGFR, and miRNAs." (PMID 38675867, 2024). "Vitamin C lowers reactive oxygen species [ROS] in tumor cells, decreasing the activity of SP transcription factors and thus the SP-dependent expression of MET and EGFR." (PMID 39062731, 2024). "The combined therapy simultaneously blocks the EGFR/VEGF pathway and downregulates signaling pathways at multiple sites, exhibiting synergistic anti-tumor activity and delaying the occurrence of TKI resistance." (PMID 38974236, 2024). "Research indicates that in NSCLC cells resistant to EGFR-TKIs, diminished expression of SFRP5 triggers the activation of the Wnt pathway, facilitating tumor advancement and drug resistance via EMT and Akt2 signaling pathways mediated by TWIST." (PMID 39196297, 2024). "Once the bioluminescent tumour signal became apparent, the animals were randomised to receive anti-mouse VEGFR2 blocking antibody (DC101), EGFR inhibitor (DAC), both, or vehicle controls (IgG, Lactate; )." (PMID 38570528, 2024). "This combination strategy targets wild-type EGFR in NSCLC and induces autophagy and tumor suppression in vivo." (PMID 38764025, 2024).